PAPSS2 (3'-phosphoadenosine 5'-phosphosulfate synthase 2)
Diseases named in the same sentence as PAPSS2 in open-access papers (continued):
Sharing a sentence is not in itself a finding about the gene and the disease.
tumor (16 papers, 2009 to 2025). "NGS results revealed that both EML4‐ALK fusion and MINPP1 and PAPSS2‐PTEN fusion were present in the patient's tumor tissue and ctDNA in blood." (PMID 33225619, 2021). "In our study, CDH1 was one of seven EMT-associated genes (CDH1, SCD, PAPSS2, C3orf52, FREM, SLC22A24, SLC25A29) successfully validated to be deregulated in tumor tissue." (PMID 27549611, 2016). "Another discovery using TCGADEPMAP was the prediction of PAPSS1 synthetic lethality with deletion of PAPSS2 and the neighboring tumor suppressor, PTEN, which were frequently co-deleted in TCGA patient tumors (43% co-incidence) yet were largely unaffected in cancer cell lines." (PMID 39009815, 2024). "In addition to impairing the tumor-suppressing roles of PTEN, the ablated metabolic functions of PAPSS2 have been linked to cancer reoccurrences, which emphasize the combined impact of collateral gene deletions in cancer cells." (PMID 37984988, 2024). "PAPSS2 gene encodes for the bifunctional 3′-phosphoadenosine 5′-phosphosulfate synthetase 2, a rate-limiting enzyme in the sulfation pathway, and it was demonstrated that depletion of PAPSS2 led to premature cell senescence in xenograft tumor mouse model and various cancer cell." (PMID 37046696, 2023). "EML4‐ALK and MINPP1 & PAPSS2‐PTEN fusions were found to be present in tumor tissue and blood." (PMID 33225619, 2021). "Moreover, we identified genes involved in cancer metabolic pathways, such as SCD and PAPSS2, in the tumor samples with EMT positive status." (PMID 27549611, 2016). "Similarly, DNA replication stress increases considerably during tumor initiation and progression and might explain the high occurrence of PAPSS2-PTEN locus deletion in cancer patients." (PMID 37984988, 2024). "Even though PAPSS2 is not significantly decreased by CNA, intra-tumor loss of PAPSS2 could favor androgen excess and hyperactivation of AR, which is critical for tumor growth and cancer progression." (PMID 30009155, 2018). "Comparing tumor cells (B-CPAP cell line) and normal cells (Nthy-ori 3-1 cell line), the expression levels of model genes (PAPSS2, ITPKA and CYP1A1) were as expected." (PMID 36685893, 2022). "The following marker genes were differentially expressed in the triphasic tumours relative to the blastemal tumours: PA (LHX1), RV/CSB/SSB (BMP2, CDH6, JAG1, PAPSS2), ePT and/or imHL (CIDEB, CLIC6, UNC5CL, VDR), and early DT/imHL (KCNJ1)." (PMID 29040332, 2017). "Furthermore, a survival analysis was conducted on the individual genes comprising the UBE2C+ tumour cell score, and it revealed statistically significant results for ITPRIP, GJA1, RUNX1T1, CD82, PAPSS2 and ANXA5." (PMID 38894657, 2024). "After controlling for tumor lineage, PAPSS1 dependency in TCGADEPMAP was correlated with significantly worse OS (hazard ratio (HR) = 0.61, P = 0.0004) in patients with PAPSS2 deletion, demonstrating that PAPSS1 is a synthetic lethality target with potentially high translational impact." (PMID 39009815, 2024). "Six genes CCSER2, AGAP11, IFIT2, PAPSS2, PCGF5, and NUDT9P1 were observed to have potential NB tumor suppressor activity since their low expression was associated with poor survival even after correction for confounding by other prognostic factors (MYCN status, age at diagnosis, stage of disease)." (PMID 37046696, 2023). "In summary, while PPARA, VDR, SLC16A1 and PAPSS2 supply the building blocks to synthesize macromolecules, GPX1 provides redox defense to counteract oxidative stress produced as a consequence of the high proliferation rates of tumor cells." (PMID 35565211, 2022). "When methylation values were compared within individual pairs of PN and PT samples, significantly higher methylation levels of PAPSS2 TUBG2, NTRK2, and SFRP4 were found in 60% (18/30), 50% (15/30), 30% (9/30), and 36% (11/30), respectively, in PN than in corresponding tumor samples (PT)." (PMID 19662090, 2009).
tumor (continued). "For each cancer type, we searched for matching gene expression and copy number datasets of at least three patients carrying homozygous deletions of these four genes (PAPSS2, ATAD1, KLLN, and PTEN) without considering other factors, such as tumor grade, age, or gender of the patients." (PMID 37984988, 2024). "Finally, PAPSS1/PAPSS2 synthetic lethality was confirmed in vivo, as demonstrated by a significant tumor growth reduction of UMUC3 tumors without PAPSS1 and PAPSS2 compared to control tumors lacking only PAPSS2." (PMID 39009815, 2024).
cancer (14 papers, 2009 to 2026). A tumor composed of atypical neoplastic, often pleomorphic cells that invade other tissues. "PAPSS1 and PAPSS2 exhibited high mutation frequencies across more than 10 cancer types, with PAPSS1 mutated in 5.8% of UCEC cases." (PMID 41441975, 2025). "Furthermore, the molecular characteristics of the PAPSS2-PTEN locus deletion that we identified in HAP1 cells can be linked to the commonly observed collateral deletion of these genes in cancer patients." (PMID 37984988, 2024). "mRNA expression analysis revealed that FOXM1 and MCM3 were upregulated, whereas SH3BP5 and PAPSS2 were downregulated in cancer tissues compared with normal tissues." (PMID 41750695, 2026). "We found that cancer cells carrying the PAPSS2-PTEN locus deletion exhibited significant changes on multiple levels, ranging from global changes in the chromatin environment to cell behavior." (PMID 37984988, 2024). "In our study the target genes are PAPSS2, SCD, and ID4 which play significant roles in various cancers." (PMID 34721037, 2021). "The three prognostic markers (PAPSS2, ANGEL2, and MPP1) that hyper‐hydroxymethylated in CIN3 also play important roles in cancers." (PMID 34323415, 2021). "As a result, we found that 3′-phosphoadenosine 5′-phosphosulfate synthase 2 (PAPSS2), γ-tubulin gene 2 (TUBG2), NTRK2, B4GALT1, and OSMR as well as SFRP4 harbored cancer-specific methylation with high frequencies (>30%)." (PMID 19662090, 2009). "First, we inspected gene aberrations of the PAPSS2, ATAD1, KLLN, and PTEN loci in 26 cancer types." (PMID 37984988, 2024). "In summary, the deletion of the PAPSS2-PTEN locus resulted in similar gene expression changes across different cancer types and may provide cancer cells with a selective advantage when exposed to external stressors, such as upon cancer treatments." (PMID 37984988, 2024).
skeletal dysplasia (10 papers, 2009 to 2025). Any Mendelian diseases that affects growth and development of the skeleton. "Papss2 shows a more restricted expression in certain tissues, such as cartilage, and mutations in Papss2 have been associated with skeletal dysplasia in humans." (PMID 40985336, 2025). "Brachyolmia 4 with mild epiphyseal and metaphyseal changes (BCYM4), also known as spondyloepimetaphyseal dysplasia Pakistani type, is an autosomal recessive inherited skeletal dysplasia caused by PAPSS2 mutation." (PMID 40927400, 2025). "This study enriched the genetic background of skeletal dysplasias, and expanded the mutation spectra of ACAN and PAPSS2." (PMID 35261200, 2022). "The present data also provides an indication of a putative defect in GAG sulfation, which may lead to dramatic biological effects, as exemplified by mutations in PAPSS2, SLC26A2, gPAPP or SUMF1, all causing skeletal dysplasias." (PMID 19898608, 2009). "This study expands the genotypic–phenotypic spectra of ACAN and PAPSS2, and highlights the important role of ACAN in short stature‐related skeletal dysplasia." (PMID 35261200, 2022).
infection (2 papers, 2012 to 2017). The state of being infected such as from the introduction of a foreign agent such as serum, vaccine, antigenic substance or organism. "To determine the effects of PAPSS2 RNAi on osteoblast gene expression, we also examined the expression of PAPSS2 using immunofluorescent staining 7 days after infection." (PMID 22916269, 2012).
metabolic disease (1 paper, 2018). A congenital disorder (due to inherited enzyme abnormality) or acquired (due to failure of a metabolically important organ) disorder resulting from an abnormal metabolic process. "Human PAPSS2 mutations manifest with undetectable DHEA sulfate, androgen excess, and metabolic disease, suggesting that ubiquitous PAPSS1 cannot compensate for deficient PAPSS2 in supporting DHEA sulfation." (PMID 29743239, 2018).
PAPSS2 also shares sentences with these, for which no sentence is quoted: androgen excess (4 papers); osteoporosis (2); thyroid cancer (2); amoebiasis (1); Antley-Bixler syndrome (1); bone disorder (1); breast tumors (1); development (1); diabetes (1); dysplasia (1); gastric cancer (1); hearing loss (1); hepatocellular carcinoma (1); Hypertension (1); invasive breast carcinoma (1); knee osteoarthritis (1); lung adenocarcinoma (1); lymphoma (1); ovarian carcinoma (1); papillary carcinoma (1); prostate adenocarcinoma (1); renal carcinoma (1); scrapie (1); skin cutaneous melanoma (1); sulphation disorders (1).